CDV3 (CDV3 homolog)
Synonyms: H41
Tractability: Antibody: its Gene Ontology location is reachable by antibodies, with high confidence; the Human Protein Atlas places it where antibodies can reach. PROTAC: ubiquitination databases record sites on it; its protein half-life has been measured.
Gene: Protein-coding gene on chromosome 3 (133,573,686 to 133,590,261, forward strand). Ensembl gene ENSG00000091527.
Subcellular location: Cytoplasm
Subcellular location (Human Protein Atlas): Cytosol; Nucleoli; Plasma membrane
Gene Ontology:
Cellular component: cytoplasm
Genetic constraint (gnomAD): Loss-of-function variants: 8 observed, 4.18 expected, observed/expected ratio (o/e) 1.91, 90% interval 0.97 to 1.96. That is too few expected variants to judge how well the gene tolerates losing a copy. Missense variants: 131 observed, 81.47 expected, observed/expected ratio (o/e) 1.61, 90% interval 1.39 to 1.85. Synonymous variants: 55 observed, 38.1 expected, observed/expected ratio (o/e) 1.44, 90% interval 1.16 to 1.79.
Homologues: Orthologues: dog CDV3 (95% identical), pig CDV3 (86% identical), mouse Cdv3 (84% identical), rat Cdv3 (83% identical), macaque CDV3 (80% identical), rabbit CDV3 (67% identical), tropical clawed frog cdv3 (53% identical), zebrafish cdv3 (48% identical).
Diseases named in the same sentence as CDV3 in open-access papers:
CDV3 is named in the same sentence as 5 diseases in open-access papers, as found by Europe PMC text mining. Sharing a sentence is not in itself a finding about the gene and the disease. The quoted sentences say what the papers report.
breast carcinoma (3 papers, 2019 to 2025). "While RAB22A has been confirmed to be associated with breast cancer metastasis, few studies have investigated ITIH3 and CDV3." (PMID 40500539, 2025). "CDV3 was documented as an unidentified gene in breast cancer, whose expression correlated to the expression of Her2 and the sensitivity of photon-irradiation and simultaneous PTX-treatment in breast cancer." (PMID 31639059, 2019).
colitis (1 paper, 2022). Inflammation of the colon. "ScRNA-seq analysis of colon and colitis showed that embryonic-specific genes reappear in response to intestinal damage, which is conserved both in human IBD and mouse DSS-induced colitis, including MYO15B, S100A11, and CDV3." (PMID 36045190, 2022).
gastric cancer (1 paper, 2011). A primary or metastatic malignant neoplasm involving the stomach. "On the other hand, CDV3 (carnitine deficiency-associated gene expressed in ventricle 3), also known as H41, seems to be involved in cell proliferation and altered in gastric cancer." (PMID 21811255, 2011).
hepatocellular carcinoma (1 paper, 2020). A malignant tumor that arises from hepatocytes. "In addition, higher CDV3 expression is associated with poor survival rate in hepatocellular carcinoma." (PMID 33193722, 2020).
CDV3 also shares sentences with these, for which no sentence is quoted: cancer (2 papers).